GCG (glucagon)
Diseases named in the same sentence as GCG in open-access papers (continued):
Sharing a sentence is not in itself a finding about the gene and the disease.
choledocholithiasis (2 papers, 2024 to 2025). Presence or formation of gallstones in the common bile duct. "The purpose of our study is to understand the change in diagnostic accuracy of IOC to detect choledocholithiasis with intraoperative glucagon." (PMID 39001295, 2024). "Hence, given the adverse events involved with ERCP, the impact of intraoperative glucagon on augmenting the diagnostic accuracy of IOC for the diagnosis of choledocholithiasis becomes even more crucial." (PMID 39001295, 2024). "Intraoperative glucagon administration is commonly performed by surgeons who are experienced in the execution of IOC as it is thought to improve diagnostic accuracy by allowing the passage of micro-choledocholithiasis and resolving air bubbles that can be falsely interpreted as filling defects." (PMID 39001295, 2024). "Given its low side effect profile, ease of use, and potential improvement in visualization during IOC, glucagon administration should be considered by surgeons when indicated during IOC to increase the yield to detect choledocholithiasis." (PMID 39001295, 2024). "The diagnostic accuracy of IOC with and without intraoperative glucagon use to diagnose choledocholithiasis has been studied in a small number of studies." (PMID 39001295, 2024). "Intraoperative glucagon administration led to improvement in the specificity (78% to 83%) and PPV (67% to 72%) of IOC (as interpreted by the operatic surgeon) to detect choledocholithiasis." (PMID 39001295, 2024). "This investigation, which involved 42 non-diabetic subjects with symptomatic choledocholithiasis, and glucagon was administered intravenously." (PMID 40943719, 2025). "Hence, our study provides an aiding tool, intraoperative glucagon during IOC, to manage patients with choledocholithiasis more effectively by determining whether ERCP is required." (PMID 39001295, 2024).
Cocaine addiction (2 papers, 2022 to 2025). "Functions related to central carbon metabolism in cancer; protein digestion and absorption, linoleic acid metabolism; mineral absorption; aminoacyl-tRNA biosynthesis; phenylalanine, tyrosine, and tryptophan biosynthesis; glucagon signaling pathway; and cocaine addiction were changed by EC at T30." (PMID 41002961, 2025).
colorectal tumors (2 papers, 2024 to 2026). "Proteomic analysis of samples from five patients with CRC revealed that glucagon expression decreased considerably in colorectal tumors compared to that in normal tissues." (PMID 38072640, 2024). "In summary, we demonstrated that glucagon can inhibit colorectal tumors by disrupting angiogenesis and vascular mimicry, which may be translated into clinical practice for further validation." (PMID 38072640, 2024).
dyspepsia (2 papers, 2021 to 2023). An uncomfortable, often painful feeling in the stomach, resulting from impaired digestion. "Fourteen genes corresponding to two gene sets were identified, and the functional dyspepsia-related genes targeted by the activated F. fructus compound were ADRA2A, BDNF, CCK, CRP, GCG, JUN, Kcnh2, PTGS1, PTGS2, Pyy, SLC6A4, and TRPV." (PMID 37375548, 2023).
eating disorder (2 papers, 2020 to 2025). A broad group of psychological disorders with abnormal eating behaviors leading to physiological effects from overeating or insufficient food intake. "The eating disorder is predicted to increase with six DRGs, which are LEP, IL6, GCG, SERPINE1, TNF, and INS." (PMID 32753925, 2020).
Headache (2 papers, 2022 to 2024). Cephalgia, or pain sensed in various parts of the head, not confined to the area of distribution of any nerve. "One experimental study published in 2017 found that the administration of insulin, glucagon, or leptin dramatically modulates the trigeminovascular system’s neuronal activity because of metabolic changes, which is a critical system in the pathogenesis of migraine headaches." (PMID 35627115, 2022).
hemochromatosis (2 papers, 2013 to 2017). A disorder of iron metabolism characterized by a triad of HEMOSIDEROSIS; LIVER CIRRHOSIS; and DIABETES MELLITUS. "Patients with hemochromatosis and impaired glucose tolerance or diabetes have enhanced glucagon responses after arginine infusion." (PMID 28331855, 2017). "When nonspecific reactivity was deducted, the resulting values for true glucagon concentrations were similar in hemochromatosis and control subjects." (PMID 28331855, 2017). "In one study, glucagon immunoreactivity in plasma was higher in patients with hemochromatosis than in control subjects, regardless of glucose tolerance." (PMID 28331855, 2017).
Hepatitis B (2 papers, 2019 to 2025). "The results identified six significantly dysregulated pathways that were involved in atropine-treated corneal epithelial cells, including glucagon signaling pathway, estrogen signaling pathway, Ras signaling pathway, insulin signaling pathway, arachidonic acid metabolism, and hepatitis B." (PMID 31540331, 2019).
hyperplasia (2 papers, 2013 to 2020). An abnormal increase in the number of cells in an organ or a tissue with consequent enlargement. "Hyperplasia of α-cells has been documented in various mouse models that have defective glucagon action, such those deficient in glucagon receptor or in prohormone convertase 2 that excise glucagon from its precursor proglucagon." (PMID 23671715, 2013).
Hypoalbuminemia (2 papers, 2023 to 2024). The concentration of albumin in the blood circulation is below the lower limit of normal. "Therefore, the interpretation of elevated glucagon levels should be combined with the presence of typical glucagonoma syndrome symptoms, including weight loss, necrotic migratory erythema, and hypoalbuminemia." (PMID 37623030, 2023). "Beyond hypoalbuminemia, an inflammatory response incites the release of growth hormones, glucagon, cortisol, and catecholamines, precipitating insulin resistance and fuel-store mobilization." (PMID 38541789, 2024).
hypogonadism (2 papers, 2020 to 2025). A disorder characterized by decreased function of the gonads. "However, interpretation of the direct effects of glucagon agonism on reproductive hormones using these agents will be challenging because the weight loss associated with these agents would be likely to improve hypogonadism if present." (PMID 32232363, 2020).
lung adenocarcinoma (2 papers, 2022 to 2025). A carcinoma that arises from the lung and is characterized by the presence of malignant glandular epithelial cells. "The preliminary TCGA dataset analysis indicated that GCG expression was downregulated in multiple cancers including COADREAD, although it was upregulated in liver hepatocellular carcinoma and lung adenocarcinoma." (PMID 35340411, 2022).
MEN1 syndrome (2 papers, 2016 to 2023). "The levels of PTH, serum calcium, glucagon and gastrin were measured, which were all in normal range excluding the clinical diagnosis of multiple endocrine neoplasia type 1." (PMID 38093965, 2023). "The combined appearance of pituitary tumors together with glucagon producing PanNETs is reminiscent of a MEN1 syndrome, in which PanNETs commonly go together with parathyroid and pituitary tumors." (PMID 27769070, 2016).
metastatic disease (2 papers, 2017 to 2018). "Glucagonoma is an aggressive pancreatic NET of glucagon-producing cells that often present with metastatic disease." (PMID 28194228, 2017). "In addition, the primary and metastatic tumors of this individual also shared high expression of the RNA encoding ghrelin; however, neither metastatic tumor carried over the expression pattern of GCG and SST RNAs seen in the primary." (PMID 30062048, 2018).
pneumonia (2 papers, 2024). An acute, acute and chronic, or chronic inflammation focally or diffusely affecting the lung parenchyma, caused by an infection in one or both of the lungs (by bacteria, viruses, fungi, or mycoplasma.). "Critical illness, including pneumonia and GI sepsis, induces the release of stress hormones such as cortisol, catecholamines, and glucagon." (PMID 39258039, 2024). "Further research is needed on the relationship between blood sugar and glucagon in pneumonia patients in ICU." (PMID 39202004, 2024).
sleep disorder (2 papers, 2022 to 2026). A change from the patient's baseline sleeping pattern, in the hours slept and/or an alteration/dysfunction in the stages of sleep. "During oral glucose tolerance test, insulin responses were attenuated, and glucagon concentrations remained consistently higher with insufficient suppression at postload time points in the sleep-disorder group." (PMID 41686553, 2026).
systemic inflammatory response syndrome (2 papers, 2022 to 2023). SIRS is a serious condition related to systemic inflammation, organ dysfunction, and organ failure. "As key systemic regulators, insulin and glucagon are critical to energy allocation in the disease syndromes relevant to systemic inflammatory response syndrome (SIRS), including ALF." (PMID 35053214, 2022).
thyrotoxicosis (2 papers, 2020 to 2025). A hypermetabolic syndrome caused by the elevation of thyroid hormone levels in the serum. "Meanwhile, thyrotoxicosis is known to increase insulin degradation and glucagon secretion, both of which contribute to the development of DKA." (PMID 41322011, 2025).
tuberculosis (2 papers, 2020 to 2022). A chronic, recurrent infection caused by the bacterium Mycobacterium tuberculosis. "Additionally, KEGG pathways of “tuberculosis,” “adrenergic signaling in cardiomyocytes,” “glucagon signaling pathway,” “galactose metabolism,” “IL-17 signaling pathway,” “phagosome,” and “Toll-like receptor signaling pathway” were significantly activated after AVF was successfully established." (PMID 35812724, 2022).
viral myocarditis (2 papers, 2019 to 2022). Myocarditis that is caused by an infection with a viral agent. "KEGG analysis revealed that the enriched pathways of up-regulated DEGs include Focal adhesion, ECM-receptor interaction, viral myocarditis, while the down-regulated DEGs were enriched in tyrosine metabolism, glucagon signaling pathway, metabolic pathways." (PMID 31772671, 2019). "The rich factor showed that the genes were mainly enriched in ribosome, proteoglycans in cancer, and glucagon signaling pathway; while the miRNAs were mainly enriched with viral myocarditis, phagosome, MAPK signaling pathway, focal adhesion, and cell adhesion molecules." (PMID 36207572, 2022).
Wolfram syndrom (2 papers, 2010 to 2016). "Notably a recent study looked directly at acute effects of subcutanous exendin-4 treatment in wild-type mice (as well as insulin-deficient Wolfram syndrom mice) and found no decrement of circulating glucagon levels." (PMID 28702245, 2016).
abdominal aortic aneurysm (1 paper, 2023). Enlargement and ballooning of the vessel that supplies arterial blood to the abdomen, pelvis and legs. "Changes in p-glucose, s-insulin, and p-glucagon between nadir and 2-hours sample after oral glucose tolerance testing in 65-year-old men with and without abdominal aortic aneurysm (AAA) at ultrasound screening." (PMID 37731907, 2023).
acute appendicitis (1 paper, 2025). "It is well known that acute appendicitis can cause stress, activating the hypothalamic-pituitary-adrenal (HPA) axis and resulting in increased secretion of various hormones, such as cortisol, norepinephrine, epinephrine, glucagon, and growth hormone." (PMID 40806903, 2025). "It is well accepted that acute appendicitis can trigger stress, activating the HPA axis and increasing the secretion of hormones like cortisol, norepinephrine, and glucagon." (PMID 40806903, 2025).
African trypanosomiasis (1 paper, 2025). "Notable pathways included base excision repair, various types of O-glycan biosynthesis, amoebiasis, the cytosolic DNA-sensing pathway, necroptosis, linoleic acid metabolism, African trypanosomiasis, glycerophospholipid metabolism, the glucagon signaling pathway, and ferroptosis." (PMID 41301995, 2025).
Airway obstruction (1 paper, 2022). Obstruction of conducting airways of the lung. "In a study on laboratory animals, it was shown that the intranasal administration of glucagon inhibits airway obstruction and reduces bronchial tree hyperreactivity and bronchoalveolar inflammation." (PMID 36291711, 2022).
autonomic diabetic neuropathy (1 paper, 2024). "These may include the lack of trophic action of insulin, glucagon, and somatostatin, autoimmune damage to the pancreas, and the presence of autonomic diabetic neuropathy, which can impair the entero-pancreatic reflex." (PMID 38398492, 2024).
AVP deficiency (1 paper, 2024). "In patients with AVP deficiency, the median copeptin at baseline was 2.1 pmol/l [1.8–2.3] and increased only slightly after glucagon injection to 3.0 pmol/L [2.4–4.1], resulting in a median increase of 0.5 pmol/l [0.2–1.7]." (PMID 38935296, 2024). "The primary objective was to determine whether glucagon stimulates OT and whether OT levels differ between patients with AVP deficiency and healthy participants." (PMID 38935296, 2024). "Similarly, in patients with AVP deficiency, the median OT at baseline was 73.9 pg/ml [65.3–81.6] and slightly increased after glucagon injection to 114.9 pg/ml [70.9–140.9], resulting in a median increase of 36.8 pg/ml [–2.2–51.2]." (PMID 38935296, 2024). "Similarly, in patients with AVP deficiency, the median OT at baseline was 73.9 pg/ml [65.3–81.6] and slightly increased after glucagon injection to 114.9 pg/ml [70.9–140.9], resulting in a change increase of 36.8 pg/ml [–2.2 to 51.2]." (PMID 38935296, 2024). "Thus, this current analysis aims to determine whether glucagon stimulates OT secretion and whether OT levels differ between patients with AVP deficiency and healthy participants." (PMID 38935296, 2024).
Biotin deficiency (1 paper, 2021). "ACACB is an enzyme that associated with diseases including Acetyl-Coa Carboxylase-Beta Deficiency and Biotin deficiency and it is related with the glucagon signalling pathway." (PMID 34085602, 2021).
cataract (1 paper, 2024). Partial or complete opacity of the crystalline lens of one or both eyes that decreases visual acuity and eventually results in blindness. "However, different eye defects such as cataracts have been observed in rat fetuses from mothers treated with glucagon during early pregnancy." (PMID 39296666, 2024).
childhood cancer (1 paper, 2019). "Testing with ITT, GHRH (with or without arginine), and glucagon has been recommended, in this order, for the diagnosis of GHD in adult survivors of childhood cancer, while no recommendations were provided for the diagnosis of GHD after adult height achievement in COGHD." (PMID 31417499, 2019).
chronic bronchitis (1 paper, 2022). A type of chronic obstructive pulmonary disease characterized by chronic inflammation in the bronchial tree that results in edema, mucus production, obstruction, and reduced airflow to and from the lung alveoli. "Glucagon, amylin and ghrelin were 2.2, 2.3 and 3.2 times lower, respectively, in the group of patients with chronic bronchitis." (PMID 36291711, 2022).
Co-infection (1 paper, 2014). "Co-infection of adult mouse pancreas with two different adenoviruses carrying Ngn3- and Mafa-induced formation of glucagon+ cells." (PMID 24714494, 2014). "We therefore used co-infection to induce glucagon+ cells in all subsequent experiments." (PMID 24714494, 2014). "In addition, co-infection of Ngn3- and Mafa-induced formation of both glucagon+ (Gcg) and somatostatin+ cells, which are distinct from each other." (PMID 24714494, 2014). "In contrast to co-infection by two separate viruses, polycistronic co-expression of Ngn3 and Mafa from a single construct yielded substantially reduced number of glucagon+ cells (less than 1%, data not shown)." (PMID 24714494, 2014).
coagulopathy (1 paper, 2022). "However, glucagonomas do not seem to be typically associated with other signs of disseminated coagulopathy, and glucagon is not known to influence the coagulation cascade." (PMID 35498123, 2022).
colonic diseases (1 paper, 2022). "GLP-2 in particular is implicated in maintenance of the intestinal mucosal integrity and barrier function by its effects on epithelial permeability, indicating the potential for therapeutic targeting of GCG and GLP in colonic diseases." (PMID 35340411, 2022).
cyst (1 paper, 2024). A sac-like closed membranous structure that may be empty or contain fluid or amorphous material. "Other areas mostly presented glucagon-positive cells and cytokeratin (CK)-positive cells that formed the epithelia of cyst-like structures." (PMID 38012450, 2024).
eosinophilia (1 paper, 2019). "Glucagon (10 and 100 μg/Kg, i.n.)significantly prevented AHR and eosinophilia in BAL and peribronchiolar region induced by ovalbumin (OVA) challenge, while only the dose of 100 μg/Kg of glucagon inhibited subepithelial fibrosis and T lymphocytes accumulation in BAL and lung." (PMID 31019244, 2019).
glycogen storage disease type VI (1 paper, 2016). "Congenital deficiency of hepatic glycogen phosphorylase (glycogen storage disease type VI or Hers disease) leads to reduced ability to mobilize glucose from glycogen in response to fasting and glucagon." (PMID 27707936, 2016).
growth failure (1 paper, 2021). "He had intellectual disability and growth failure (11.3 cm/year in first year of life), with GHD diagnosed at the age of 1.4 years (GH peak on glucagon test of 2.4 μg/L) when GH treatment was started (0.019 mg/kg/day)." (PMID 33950863, 2021).
helminth infection (1 paper, 2025). "The pancreas- and ileum-related DEGs (n = 26) reinforced the need for digestive enzymes and glucagon to power the return to homeostasis in response to helminth infection." (PMID 40559579, 2025).
hyperamylasemia (1 paper, 2024). Abnormally high level of amylase in the blood. "Additionally, though we found hyperamylasemia and hyperlipasemia after hepatectomy for living liver donors, we have not yet clarified the involvement of pancreatic hormones such as glucagon and insulin." (PMID 38514681, 2024).
hyperandrogenism (1 paper, 2017). Excessive secretion of androgens from the adrenal glands or gonads. "Given that hyperandrogenism is a hallmark of PCOS and that CFTR can be upregulated by androgen, we suspected that the suppressed glucagon in PCOS could be due to androgen-induced upregulation of CFTR." (PMID 29204121, 2017).
Hypercholesterolemia (1 paper, 2021). An increased concentration of cholesterol in the blood. "The hypercholesterolemia recorded during lactation suggests lipid mobilization mediated by glucagon, an acute synthesis of plasma lipoproteins, an important feed intake for milk synthesis, or the estrogens that stimulate CHO synthesis." (PMID 34840462, 2021).
injury (1 paper, 2017). Damage inflicted on the body as the direct or indirect result of an external force, with or without disruption of structural continuity. "Traumatic brain injury initiates a dramatic systemic stress response with the release of cortisol, catecholamines, and glucagon leading to excessive hepatic gluconeogenesis and peripheral insulin resistance." (PMID 28993802, 2017).
intestinal neuroendocrine tumor (1 paper, 2010). "To summarize, the laboratory blood and solid tissue results revealed an intestinal neuroendocrine tumor producing a non-pancreatic form of glucagon: enteroglucagon." (PMID 20550685, 2010).
motor neuron diseases (1 paper, 2021). "Defects in glucagon and insulin-producing pancreatic islets, as well as increased circulating levels of glucagon, albeit not as profound as in SMA, are significant observations made in both motor neuron diseases." (PMID 34072857, 2021).
Mydriasis (1 paper, 2018). Abnormal dilatation of the iris. "Adrenaline is an important hormone in the response to stress because it increases glucagon concentration, which stimulates an increase in glucose and blocks insulin production thereby increasing heart rate, decreasing gastrointestinal motility, causing mydriasis, and increasing muscle energy." (PMID 30425790, 2018).